TRPM7 (transient receptor potential cation channel subfamily M member 7)
Diseases named in the same sentence as TRPM7 in open-access papers (continued):
Sharing a sentence is not in itself a finding about the gene and the disease.
TRPM7 also shares sentences with these, for which no sentence is quoted: Cerebral ischemia (4 papers); Parkinsonism (4); benign prostatic hyperplasia (2); breast ductal adenocarcinoma (2); breast invasive carcinoma (2); colon (2); graft versus host disease (2); hyperplastic polyp (2); Jalili syndrome (2); Myalgic Encephalomyelitis (2); sick sinus syndrome (2); squamous cell lung carcinoma (2); adenosquamous carcinoma (1); amblyopia (1); anaemia (1); Arterial thrombosis (1); autoimmune hepatitis (1); bladder tumor (1); brain diseases (1); brain tumors (1); cardiac arrhythmia (1); cerebral infarction (1); chronic kidney disease (1); colitis (1); colorectal (1); Crohn disease (1); cutaneous melanoma (1); dementia (1); diffuse astrocytoma (1); endometriosis (1).
A further 34 diseases each share a sentence with TRPM7 in 1 paper.